CLCN5 (Cl-/H+ antiporter 5)
Diseases named in the same sentence as CLCN5 in open-access papers (continued):
Sharing a sentence is not in itself a finding about the gene and the disease.
Dent disease (continued). "Around 50%–60% of patients carry pathogenic variants in the CLCN5 gene (Dent disease type 1 [DD1] Online Mendelian Inheritance in Man 300009), and 10%–15% of patients carry pathogenic variants in the OCRL gene (Dent disease type 2 Online Mendelian Inheritance in Man 300555)." (PMID 38814756, 2024). "In addition to a novel nonsense variant in CLCN5, our patient presents other findings atypical of Dent disease." (PMID 39610999, 2024). "DD caused by genetic changes in the CLCN5 gene is known as Dent disease-1 (DD1) (OMIM #300009)." (PMID 38002082, 2023). "Dent disease (DD1) is a rare tubulopathy caused by mutations in the CLCN5 gene." (PMID 36674829, 2023). "Similarly, mutation in CLCN5 can lead the occurrence of renal tubular acidosis, proteinuria, hypercalciuria, renal calcification, kidney stones, and Dent disease." (PMID 36408280, 2022). "When CLCN5 is mutated, it causes Dent’s disease, a rare kidney disorder." (PMID 35323942, 2022). "Inactivating mutations of CLCN5 in Dent disease patients as well as the deletion of CLCN5 in knock-out (KO) mice lead to severe LMWP due to a defective endocytic uptake in PTCs, which has been associated with the disappearance of megalin and cubilin at the brush border of PTCs." (PMID 33987651, 2021). "Dent disease is a rare X-linked renal tubulopathy due to CLCN5 and OCRL (DD2) mutations." (PMID 34680992, 2021). "In addition to Dent disease, CLCN5 associated disease have a variable phenotype including focal segmental glomerulosclerosis (FSGS), and the OCRL path variants are also associated with Oculocerebrorenal syndrome." (PMID 33430795, 2021). "However, there are no comprehensive reports of suspected splicing variants in the CLCN5 gene in Dent disease cases." (PMID 32201916, 2020). "Dent disease 1 (CLCN5 mutations) accounts for 60% of Dent disease cases." (PMID 31935940, 2020). "Interestingly we also identified a hemizygous mutation in CLCN5 in the male proband with a diagnosis of Dent disease." (PMID 32725812, 2020). "There is genetic heterogeneity for Dent disease, with approximately 60% of patients having CLCN5 mutations (Dent disease 1), ~15% harboring OCRL1 mutations (Dent disease 2) and the remaining 25% of patients having neither CLCN5 nor OCRL1 mutations but possibly defects in other genes." (PMID 25670966, 2015). "However, hypercalciuria, the most important metabolic abnormality associated with Dent disease, was associated with concomitant nephrolithiasis only in CLCN5+ patients." (PMID 26389017, 2015). "The disruption and partial loss of CLCN5 confirmed the diagnostic of Dent disease for this patient." (PMID 25670966, 2015). "Mutations of the human gene encoding ClC-5 (CLCN5 gene) cause the X-linked disorder of the proximal tubules known as Dent’s disease, which is characterized by low-molecular-weight proteinuria, hypercalciuria, nephrolithiasis, aminoaciduria, phosphaturia, and renal failure." (PMID 25019425, 2014). "Dent's disease is an inherited tubulopathy caused by CLCN5 gene mutations." (PMID 21859490, 2011). "Thus, there is genetic heterogeneity for Dent's disease, with approximately 50-60% of patients having CLCN5 mutations (Dent disease 1), ~15% harbouring OCRL1 mutations (Dent disease 2) and the remaining 25-35% of patients having neither CLCN5 nor OCRL1 mutations but possibly defects in other genes." (PMID 20946626, 2010). "The size differences observed between healthy controls and patients with Dent's disease were attributed to mutations in CLCN5, which led to alterations in ClC-5 localized in early endosomes, thus impacting the production and release of exosomes." (PMID 40873806, 2025). "CLCN5 variants were detected in 19 patients (Dent disease type 1, DD1), and OCRL variants were identified in 4 patients (Dent disease type 2, DD2)." (PMID 41361832, 2025).
Dent disease (continued). "Approximately 60% of cases are attributed to pathogenic variants in the CLCN5 gene, which characterize Dent disease type 1 (DD1), while 15% are associated with pathogenic variants in the OCRL gene, defining Dent disease type 2 (DD2)." (PMID 41361832, 2025). "These include Dent disease (CLCN5, OCRL), AD tubulointerstitial kidney disease (ADTKD due to UMOD variants), nephronophthisis (TTC21B, NPHP4), Imerslund-Grasbeck syndrome 1 (CUBN) and papillorenal syndrome (PAX2)." (PMID 37578539, 2024). "When a pathogenic variant in CLCN5 disrupts the CIC-5 protein's proper functioning, tubular proteinuria occurs as well as hypercalciuria leading to the various manifestations of Dent disease." (PMID 39610999, 2024). "In 2008, the carbonic anhydrase type III (CA III) kidney-specific upregulation was described in the context of Dent disease type 1 (patient and Clcn5 KO mice)." (PMID 39336766, 2024). "Two-thirds of cases are associated with inactivating variants in the CLCN5 gene (Dent disease 1, DD1) and a few present variants in the OCRL gene (Dent disease 2, DD2)." (PMID 38002082, 2023). "Dent disease type 1 is a heterotypic X-linked disease caused by mutations in CLCN5, which encodes the electrogenic Cl−/H+ exchanger CLC-5, localized in early endosomes of the proximal tubule (PT)." (PMID 37799275, 2023). "For example, the gene CLCN5 is a disease gene for Dent disease 1 (MIM: 300009), a recognised renal tubulopathy." (PMID 36477409, 2023). "As for the diagnosis of Dent disease, patient SOR0118 had a likely pathogenic variant in the CLCN5 gene in the hemizygous state, according to the expected transmission pattern." (PMID 37537162, 2023). "Mutations in CLCN5, encoding the chloride channel Cl−/H+ exchanger ClC-5, have been identified in FSGS patients with Dent disease using exome sequencing." (PMID 35223901, 2022). "It is caused by mutations in the chloride voltage-gated channel 5 (CLCN5) gene (Dent disease-1), or in the OCRL gene (Dent disease-2)." (PMID 35549682, 2022). "Dent disease (with inclusion of CLCN5 and OCRL1 genes) and primary hyperoxaluria (PH) (with inclusion of AGXT and HOGA1 genes) were identified with high frequency." (PMID 35612621, 2022). "Four patients had causative mutations in the CLCN5, OCRL genes, which are associated with Dent disease, and a heterozygous mutation of the PHEX gene was detected in a patient diagnosed with XLH." (PMID 35612621, 2022). "While a role for CLCN5 in Dent disease was suggested in 1994, it was only 11 years later that OCRL was identified as a second disease-causing gene." (PMID 34680992, 2021). "It is becoming increasingly clear that CLCN5 and OCRL gene mutations cannot account for all Dent disease patients." (PMID 32860533, 2021). "Up until now, due to its heterogeneity, only 2 genes have been identified: CLCN5 (Dent disease type 1–60% of cases) and OCRL1 (Dent disease type 2–15% of cases)." (PMID 33150036, 2020). "In Dent disease, first experience with bone marrow transplantation in Clcn5 knockout mice, a model for Dent disease, showed an improvement of protein-, calci-, and glucosuria as well as reduced polyuria." (PMID 29707529, 2018). "Patients with a mutation in CLCN5 are classified as having Dent disease type 1 (Dent-1; MIM #300009), while patients with a mutation in OCRL are classified as Dent disease type 2 (Dent-2; MIM #300555)." (PMID 27757584, 2017). "As CLCN5 and OCRL mutations impair the function of the megalin–cubilin system, the loss of LMW proteins is an obligate finding in Dent disease." (PMID 27757584, 2017). "It is tempting to extrapolate findings from patients with Dent disease type 1 (Dent-1 disease) who harbor defects in CLCN5 leading to impaired megalin–cubulin receptor-mediated endocytosis in the proximal tubule." (PMID 27011217, 2016).
Dent disease (continued). "On the basis of some reports of patients with Dent-1 disease, whose initial clinical presentation was proteinuria with LMWP but without hypercalciuria, we decided to screen our patient for CLCN5 and OCRL1 mutations." (PMID 26108450, 2015). "For our patient, the Xp11.22 deletion including CLCN5 and, consequently, the loss of CIC-5 exchanger allowed us to confirm the diagnosis of Dent disease." (PMID 25670966, 2015). "The mutations in the voltage-sensitive chloride channel genes CNCNKB, CLCN1, CLCN5, and CLCN7 have been linked to Bartter syndrome, myotonia congenita, Dent disease, and osteopetrosis, respectively." (PMID 25794116, 2015). "Our findings highlight the structural complexity of the CLCN5 5′UTR region in renal and extrarenal tissues, and suggest that this region is likely involved in ClC-5 expression and Dent disease pathogenesis." (PMID 25001568, 2014). "In approximately 60% of patients, the disease is caused by inactivating variants in the CLCN5 gene (Online Mendelian Inheritance in Man No. 300009; Dent disease type 1, DD1) located on the short arm of the X chromosome (Xp11.22)." (PMID 40420588, 2025). "The Renal proteinuria gene list corresponded to some genetic kidney diseases (CAKUT, tubulopathies, ciliopathies) that result in secondary FSGS such as Dent disease (CLCN5, OCRL), nephronophthisis (TTC21B, NPHP4), ADTKD-UMOD and Imerslund-Grasbeck syndrome 1 (CUBN)." (PMID 37578539, 2024). "UMOD, CLCN5, OCRL, NPHP4, and TTC21B may cause tubulointerstitial diseases such as ADTKD, NPHP, or Dent disease, but they are now included in the genetic panels for genetic screening of patients affected by FSGS, as they can phenocopy it." (PMID 37728640, 2024). "Mutations in the CLCN5 and OCRL genes are known to cause Dent disease." (PMID 37799275, 2023). "A pathogenic variant in CLCN5 accounts for 60% of those with Dent disease (known as Dent disease-1, DD1) whereas a pathogenic variant in the OCRL gene accounts for another 15% (known as Dent disease-2, DD2)." (PMID 35549682, 2022). "Intriguingly, although LMWP is considered the clue to a diagnosis of Dent disease, two males with CLCN5 mutations reportedly had no LMWP at the time of their diagnosis, but they did have other symptoms of Dent disease, such as hypercalciuria." (PMID 32860533, 2021). "In approximately 65% of patients, mutations of chloride voltage-gated channel 5 gene (CLCN5) are responsible for Dent disease type 1, while in 10–15% of patients, mutations in the oculocerebrorenal syndrome of Lowe gene (OCRL) cause Dent disease type 2." (PMID 33625696, 2021). "DNA sequencing showed a deletion of G at nuleotide 1444 in exon 11 of the CLCN5 gene [NM_001127899; c.1444delG] and the deletion led to a downstream ochre codon (TAA) mutation at nuleotide 1509 in exon 11 [p.L503*] (pathogenic, Dent disease 1, X-linked recessive) in this child." (PMID 33430795, 2021). "Dent disease-1 is caused by pathogenic variants in the chloride voltage-gated channel 5 (CLCN5) gene located on chromosome Xp11.23, which encodes the kidney specific electrogenic chloride/proton (Cl−/H+) exchange transporter ClC-5." (PMID 29084614, 2017). "In summary, patients with Dent 1 disease have a variety of clinical manifestations that seem not directly linked to the specific CLCN5 mutation." (PMID 27117801, 2016). "Dent disease 1 (OMIM 300009) is an X-linked recessive disorder of renal tubular epithelial function, associated with genetic variation of the CLCN5 gene that encodes the ClC-5 Cl-/H+ antiporter." (PMID 25001568, 2014). "5′UTR exons that are commonly present among expressed isoforms are candidates for mutation analysis of Dent disease patients without genetic variation in the CLCN5 coding region." (PMID 25001568, 2014). "Indeed heterologous expression of these Dent's disease CLCN5 mutants, in either Xenopus laevis oocytes or HEK293 cells, has revealed that the majority of CLCN5 mutations lead to a loss of Cl- conductance." (PMID 20946626, 2010).
Dent disease (continued). "A few patients with Dent's disease do not harbour mutations in CLCN5 and OCRL1, pointing to the involvement of other genes." (PMID 20946626, 2010). "Approximately 40% of patients with Dent's disease do not have CLCN5 mutations, even though they are clinically indistinguishable from those that have CLCN5 mutations." (PMID 20946626, 2010). "The gene causing Dent’s disease, CLCN5, encodes the chloride/proton antiporter CLC-5." (PMID 18446382, 2009). "Although more than 150 different mutations have been reported within the CLCN5 coding exons, patients with typical symptoms of Dent disease 1 have been genotyped by our group and others in whom no mutations could be detected." (PMID 25001568, 2014). "Megalin dysfunction has also been demonstrated in Dent disease, caused by a mutation in the chloride channel CLCN5, which results in low-molecular-weight proteinuria and urinary VDBP loss in humans, similar to mice deficient in the CLCN5 gene and protein product, CLC-5." (PMID 21747824, 2011). "They proposed CLCN5 as the candidate gene, not only for Dent disease, but also for XRN and XLRH, shedding light on the marked phenotypic heterogeneity of Dent disease." (PMID 32860533, 2021). "However, in both diseases, the mutations are not in the trafficking machinery; Dent disease is caused by mutation in the endosomal chloride channel chloride channel protein 5 (ClC-5; also known as CLCN5), and cystinosis by mutation of a lysosomal cystine transporter." (PMID 32433026, 2020). "Two interstitial microdeletions Xp11.22 including the CLCN5 and SHROOM4 genes were recently reported in a male individual affected with Dent disease, short stature, psychomotor delay and minor facial anomalies." (PMID 30630535, 2019). "While finding CLCN5 and OCRL mutations unquestionably leads to a diagnosis of Dent disease, it sheds no light on the disease’s phenotypic heterogeneity." (PMID 32860533, 2021). "Although mutations on the CLCN5 and OCRL genes are known to cause Dent disease, no such mutations are found in about 25–35% of cases, making diagnosis more challenging." (PMID 32860533, 2021). "No CLCN5 mutations were identified among these patients, confirming the low rate of DD1 among pediatric populations with FSGS, as well as in other selected diagnoses that could be confused clinically with Dent disease." (PMID 32860533, 2021).
Hypercalciuria (24 papers, 2010 to 2025). "Only in patients harbouring CLCN5 mutations was age-independent nephrolithiasis associated with hypercalciuria, suggesting that nephrolithiasis is linked to altered proximal tubular function caused by a loss of ClC-5 function, in agreement with ClC-5 KO animal models." (PMID 26389017, 2015). "The authors recommended screening for CLCN5 and/or OCRL mutations in all males presenting with LMWP irrespective of any additional clinical features (nephrolithiasis or nephrocalcinosis, hypercalciuria, rickets, or CKD)." (PMID 32860533, 2021). "The presence of nephrocalcinosis or nephrolithiasis in a patient prior to initiation of therapy, suggests diseases associated with hypercalciuria such as HHRH (NaPi 2C defects), Dent disease 1(CLCN5 defect) or hypophosphatemia and nephrocalcinosis (NaPi2a defects)." (PMID 34910242, 2022). "The triad of symptoms, LMWP, hypercalciuria, and nephrocalcinosis, was present in almost all patients with CLCN5 mutations but not in those without CLCN5 mutations." (PMID 26389017, 2015). "Furthermore, BDs were neither significantly different between the CLCN5+ and CLCN5− patients nor significantly associated with the presence of hypercalciuria." (PMID 26389017, 2015). "The findings indicated that, even in the absence of a decrease in 1,25-dihydroxyvitamin D3, hypercalciuria in Clcn5 KO mice originates in the bone and kidney." (PMID 32860533, 2021). "The mechanism by which hypercalciuria arises in CLCN5− patients is unknown, but the significantly lower frequency with which it was found in our CLCN5− patients with respect to the CLCN5+ patients suggests that the endocytosis-mediated proximal calcium reabsorption is intact." (PMID 26389017, 2015). "Thus, in the majority of CLCN5− patients and in the CLCN5+ family, nephrolithiasis was associated neither with nephrocalcinosis nor with hypercalciuria." (PMID 26389017, 2015).
nephrolithiasis (16 papers, 2010 to 2024). The presence of a calculus in the pelvis of the kidney; this is most often composed of mineral salts and proteins. "Additionally, individuals with truncating variants in CLCN5 experienced kidney stones earlier and a higher stone burden had a positive correlation with CKD evolution." (PMID 39610999, 2024). "In contrast, in the CLCN5+ family, nephrolithiasis was present only in the three adults aged 38–46 years." (PMID 26389017, 2015). "Nephrolithiasis, however, was significantly (p = 0.011) more frequent in adults (12/28) than in children (3/30), but the median age of adult patients with nephrolithiasis was significantly lower in CLCN5+ than in CLCN5− group (23 vs. 42 p = 0.012)." (PMID 26389017, 2015). "We found that the distribution of nephrolithiasis, bone disorders and CKD differs among patients with and without CLCN5 mutations." (PMID 26389017, 2015).
nephrocalcinosis (12 papers, 2010 to 2025). Nephrocalcinosis is a disorder that occurs when too much calcium is deposited in the kidneys. "Similarly, only in patients harbouring CLCN5 mutations was age-independent kidney failure associated with nephrocalcinosis, suggesting that kidney failure is the consequence of a ClC-5 dysfunction, as in ClC-5 KO animal models." (PMID 26389017, 2015).
Lowe syndrome (9 papers, 2015 to 2021). "CLCN5 encodes the electrogenic chloride/proton exchanger ClC-5 which is involved in the tubular reabsorption of albumin and LMW proteins, OCRL encodes the inositol polyphosphate 5-phosphatase, and was initially associated with Lowe syndrome." (PMID 26389017, 2015).
cystinosis (4 papers, 2020 to 2021). Cystinosis is a metabolic disease characterized by an accumulation of cystine inside the lysosomes, causing damage in different organs and tissues, particularly in the kidneys and eyes. "Besides CLCN5 (DD1) and OCRL (Lowe syndrome and Dent disease type 2) genes, they include LRP2 (DB/FOAR), CUBN, AMN (Imerslund–Gräsbeck syndrome), and CTNS (nephropathic cystinosis)." (PMID 31947599, 2020).
renal tubular disorder (4 papers, 2010 to 2022). "In respect to CLCN5, mutations in its sequence have been proven to be associated with diseases of renal tubules, resulting in chronic renal failure." (PMID 25288656, 2014).
central nervous system cancer (2 papers, 2015 to 2020). "Corroboration that CLCN5 CNVs are associated with the Axon guidance pathway comes from the observation that 65.9% of central nervous system cancers have a loss of one or two copies of the CLCN5 gene (COSMOS,)." (PMID 25965968, 2015).
Chronic Lymphocytic Leukemia (2 papers, 2015 to 2025). "CLCN5 has also been implicated in proteinuria and chronic lymphocytic leukemia." (PMID 40765554, 2025).
hepatocellular carcinoma (2 papers, 2015 to 2019). A malignant tumor that arises from hepatocytes. "While the roles of Ankrd52 and Clcn5 in liver disease remain unclear, Peg10 has been widely studied in hepatocellular carcinoma (HCC) pathology." (PMID 31470644, 2019).
nephronophthisis (2 papers, 2022 to 2024). Progressive tubulointerstitial injury, inherited in an autosomal recessive pattern, caused by mutations in genes involved in ciliary function, which may result in an end stage renal failure. "This can be the case with UMOD variants or CLCN5, usually associated with tubular dysfunction, or the mutations in type IV collagen genes and nephronophthisis genes." (PMID 35207681, 2022).